MSR1 (macrophage scavenger receptor 1)
Diseases named in the same sentence as MSR1 in open-access papers (continued):
Sharing a sentence is not in itself a finding about the gene and the disease.
lung fibrosis (7 papers, 2013 to 2022). "Stimulation with collagen-type monomers significantly upregulated MSR1 expression in alveolar macrophages from patients with idiopathic pulmonary fibrosis, suggesting a potential role of MSR1 for the development of lung fibrosis." (PMID 33604393, 2021). "We assess not only the correlation between MSR1- or CD86-expressed macrophages and clinicopathological factors of lung fibrosis but also its influence on the survival after lung transplantation." (PMID 33604393, 2021). "Since the expression of MSR1 correlated significantly with functional indices (FEV1, FVC) of lung fibrosis severity, it could be a useful biomarker in the assessment of the clinical status of patients with IPF." (PMID 33604393, 2021). "In summary, our data imply that an increased MSR1, IL-13, and Arg1 expression occurs in patients with IPF, an observation that could suggest a possible role for M2 macrophages in the pathogenesis of pulmonary fibrosis." (PMID 33604393, 2021).
viral infections (7 papers, 2012 to 2024). "Previous studies have demonstrated that the physiological functions of MSR1 during viral infections vary with viral species and disease models." (PMID 33033362, 2020). "However, the current literature about the physiological function of MSR1 in viral infections is inconsistent." (PMID 33033362, 2020). "RNAi-mediated knockdown of MSR1 expression blocks TLR3 sensing of HCV in infected hepatocyte cultures, leading to increased cellular permissiveness to virus infection." (PMID 23717201, 2013). "Besides, phagocytosis or anti-viral activity-related genes (such as MSR1, CD36) or viral protein interactions with cytokine-cytokine receptors, were upregulated in iM2φ following viral infection." (PMID 35440562, 2022).
chronic obstructive pulmonary disease (6 papers, 2014 to 2022). A chronic and progressive lung disorder characterized by the loss of elasticity of the bronchial tree and the air sacs, destruction of the air sacs wall, thickening of the bronchial wall, and mucous accumulation in the bronchial tree. "Not only are MSR1 levels linked to lung injury, but also the MSR1-coding SNP P275A in macrophages was associated with susceptibility to chronic obstructive lung disease in smokers." (PMID 36325338, 2022). "With regard to the respiratory system, several studies have found an association between polymorphisms and overexpression of MSR1 in human macrophages from chronic obstructive pulmonary disease (COPD)." (PMID 35268530, 2022). "Alveolar macrophages also limit pulmonary inflammation, in chronic obstructive pulmonary disease and asthma, after oxidant inhalation by utilising MSR1 to scavenge proinflammatory oxidised lipids." (PMID 36325338, 2022).
ischemic stroke (6 papers, 2017 to 2024). A stroke disorder caused by obstruction of blood flow to the brain, due to thrombotic (local blood clot formation) or embolic (due to a blood clot or other material traveling from another site) event. "From day 3 post ischemic stroke, MSR1-expressing macrophages increased, scavenging HMGB1 and PRX until 1 week post ischemic stroke." (PMID 36671605, 2022). "In previous studies, the expression of Msr1 was enhanced by Mafb and eliminates DAMPs following ischemic stroke via endocytosis to reduce the release of inflammatory cytokines by exogenous ligands." (PMID 35237277, 2022). "Furthermore, resolution of neuropathology in a model of ischemic stroke occurs through the clearance of damage signals, debris, and revascularization by macrophage scavenger receptor 1 (MSR1)." (PMID 39095837, 2024). "Interestingly, other studies have suggested a possible role for Msr1 in modulating the degree of damage following ischemic stroke by enhancing phagocytic activities in macrophages and microglia to resolve inflammation." (PMID 34408625, 2021).
oral squamous cell carcinoma (6 papers, 2017 to 2025). "MSR1 glycosylation appears to be relevant to its function since the N102K mutation has been linked to oral squamous cell carcinoma (COSMIC ID: 3715901)." (PMID 36325338, 2022).
Stroke (6 papers, 2021 to 2025). Sudden impairment of blood flow to a part of the brain due to occlusion or rupture of an artery to the brain. "In an experimental stroke model tamibarotene enhanced expression of both MafB and MSR1, and in turn reduced the infarct volume." (PMID 33670976, 2021). "Next, we examined the expression of V-maf musculoaponeurotic fibrosarcoma oncogene homolog B (MAFB) and MSR1 in the ipsilateral brain hemisphere, the function of which is to clear DAMPs (e.g., Prx1) after stroke." (PMID 34162400, 2021). "Immunofluorescence analysis 24 h after stroke corroborated Msr1 and LCN2 expression." (PMID 38988493, 2024). "However, unknown is whether MSR1 may accelerate the resolution of inflammation through direct induction of the phagocytosis of dead/dying cells (e.g., apoptotic neurons) after stroke." (PMID 34162400, 2021).
Insulin resistance (5 papers, 2014 to 2024). Increased resistance towards insulin, that is, diminished effectiveness of insulin in reducing blood glucose levels. "We next used radiolabeled glucose tracer and whole‐body imaging after insulin injection in 6‐week HFD‐fed WT and Msr1−/− mice in order to determine tissue‐specific insulin resistance." (PMID 30485705, 2018). "Genetic deletion of Msr1 or feeding fucoidan, a natural product ligand of MSR1, both worsened insulin resistance and blood glucose control." (PMID 30485705, 2018). "Our results show that ligand or gene targeting of MSR1 exacerbates insulin resistance in obese mice." (PMID 30485705, 2018). "In further support of Msr1 deletion worsening HFD‐induced insulin resistance, we found that 10 weeks of HFD‐feeding caused higher blood glucose during a GTT in Msr1−/− mice compared to WT and Marco−/− mice." (PMID 30485705, 2018). "Our results build on this previous work by showing that MSR1 provides a unique protection from excessive insulin resistance compared to other Class A scavenger receptors, since MARCO was dispensable for changes in insulin sensitivity in obese mice." (PMID 30485705, 2018). "Similar worse insulin resistance was observed in Msr1−/− mice fed HFD for 16 weeks." (PMID 36788340, 2023). "MSR1 expression in subcutaneous adipose tissue (SAT) is associated with insulin resistance in non-diabetic patients." (PMID 36788340, 2023). "We found that genetic deletion of Msr1 exacerbated adipose tissue insulin resistance." (PMID 30485705, 2018). "MSR1 and MARCO sense lipoproteins that have been implicated in cardiovascular disease, but the roles for different Class A scavenger receptors in carbohydrate metabolism and insulin resistance are ill‐defined." (PMID 30485705, 2018). "We hypothesized that adipose tissue inflammation could underpin adipose insulin resistance observed in HFD‐fed fucoidan‐treated WT mice or Msr1−/− mice." (PMID 30485705, 2018). "first demonstrated that fucoidan binds to MSR1 at the LDL recognition site of macrophages, numerous studies have found that fucoidan can lower blood glucose and improve insulin resistance, steatosis, endoplasmic reticulum stress and inflammation in obese mice and rats." (PMID 36591228, 2022). "MSR1, KYNU, and RBKS, but not SMPD1, were associated with metabolic and liver dysfunction markers, while SCARA5, TNFRSF12A, SMOC2, but not GDF-8, were associated with insulin resistance markers." (PMID 39407757, 2024).
thymic carcinoma (5 papers, 2021 to 2025). Thymic carcinoma (TC) is a type of thymic epithelial neoplasm characterized by a high malignant potential. "Similar prognostic value was confirmed in thymic carcinoma where the ratio of CD8+ T cells/MSR1+ TAMs and CD20+ B cells/MSR1+ TAMs indicated prognostic effect in the stroma." (PMID 36325338, 2022).
acute coronary syndrome (4 papers, 2010 to 2022). Signs and symptoms related to acute ischemia of the myocardium secondary to coronary artery disease. "Few published studies have analyzed the expression of MSR1 on the surface of PBMCs, and those that have evidenced expression have done so in subsets of monocytes in diseases such as acute coronary syndromes and in systemic sclerosis." (PMID 35268530, 2022). "Increased expression of MSR1 in peripheral blood mononuclear cells has been found in patients with acute coronary syndrome." (PMID 23554780, 2012).
coronary artery disease (4 papers, 2012 to 2021). "For example, the scavenger receptors MSR1, CD36, and LOX-1 have been shown to bind modified LDL particles, which play a prominent role in CMD and coronary artery disease." (PMID 25224267, 2014).
COVID-19 (4 papers, 2021 to 2025). A disease caused by infection with severe acute respiratory syndrome coronavirus 2. "Decreased phagocytosis in severe COVID-19 was evident by the downregulation of MSR1, Neuropilin 1 (NRP1), and MRC1, with more significant decreases in SevereD." (PMID 39928675, 2025). "High plasma levels of MSR1, as well as high CSF TNFRSF12A and IL-8 levels demonstrated the most robust association with COVID-19 severity." (PMID 36351919, 2022).
Granuloma (4 papers, 2012 to 2025). A compact, organized collection of mature mononuclear phagocytes, which may be but is not necessarily accompanied by accessory features such as necrosis. "In non-necrotic granulomas at 8 weeks p.i., localization of MSR1 or LGALS3 was consistent with that of PLIN2, suggesting that these two proteins are also the marker for FM in non-necrotic granulomas." (PMID 36237431, 2022).
hepatocellular carcinoma (4 papers, 2021 to 2025). A malignant tumor that arises from hepatocytes. "MSR1 transcript levels are significantly associated with the incidence of hepatic steatosis, cirrhosis, and hepatocellular carcinoma in patients with NAFLD; and MSR1 protein expression also increases with disease progression." (PMID 36591228, 2022). "In chronic liver inflammation, MSR1 transcript levels are significantly correlated with the incidence of hyperlipidemia, cirrhosis and hepatocellular carcinoma." (PMID 36591228, 2022).
influenza (4 papers, 2012 to 2024). An acute viral infection of the respiratory tract, occurring in isolated cases, in epidemics, or in pandemics; it is caused by serologically different strains of viruses (influenzaviruses) designated A, B, and C, has a 3-day incubation period, and usually lasts for 3 to 10 days. "Influenza infection significantly decreased mRNA level of macrophage receptors CLEC7A, MSR1, CD36, and MRC1." (PMID 22396727, 2012).
Sepsis (4 papers, 2020 to 2022). Sepsis is defined as life-threatening organ dysfunction caused by a dysregulated host response to infection. "MSR1 activation can also lead to excessive inflammation linked to sepsis and worsening the cardiac and cerebral injury." (PMID 34857772, 2021). "Several studies indicate that MSR1 ameliorates sepsis by suppressing the pro-inflammatory response, in particular by reducing TNF-α signalling and TLR4-induced activation of NF-κB, potentially by limiting the availability of free LPS." (PMID 36325338, 2022). "Further to its role in bacterial immune response, MSR1 has a complex and contradictory role in endotoxemia or systemic inflammation, often used as a model substitute for sepsis despite clear disparities and limitations in their nature." (PMID 36325338, 2022). "In sepsis studies simulated with LPS, Msr1-/- mice survived at a lower rate than wild type mice, and this protective effect is associated with the anti-inflammatory effect of MSR1 in dendritic cells." (PMID 36591228, 2022). "MSR1 played a clear detrimental role in the disease pathophysiology of the cecal ligation and puncture model of sepsis, enhancing pro-inflammatory signalling through interaction with TLR." (PMID 36325338, 2022). "In another LPS-induced sepsis model, MSR1+ monocytes and/or macrophages also inhibit the acute inflammatory response by suppressing the upregulation of TNF-α and IL-6 levels." (PMID 36591228, 2022). "Therefore, the controversial role of MSR1 in sepsis could be masked by the activation of other receptors by LPS." (PMID 36325338, 2022).
steatosis (4 papers, 2012 to 2024). Increased lipid within the cytoplasm of cells. "Macrophage scavenger receptor 1 (MSR1, CD204) mediates lipid uptake and accumulation in KCs and correlates with the degree of steatosis and steatohepatitis in patients with NAFLD." (PMID 36742318, 2023). "Msr1 transcript levels were found to correlate with the degree of steatosis and steatohepatitis in human NAFLD patients and a polymorphism upstream of Msr1 was strongly correlated with aspartate aminotransferase and serum triglyceride levels." (PMID 36994095, 2023).
Barrett esophagus (3 papers, 2021 to 2024). Esophageal lesion lined with columnar metaplastic epithelium which is flat or villiform. "MSR1 mutations are also involved in Barrett esophagus (BE) and esophageal adenocarcinoma (EAC) development." (PMID 36686729, 2022).
chronic myeloid leukaemia (3 papers, 2013 to 2024). "The analysis also singled out ROBO2 (deleted in 9% of cases and mutated in 3%) a candidate tumor suppressor in head and neck cancer, and MSR1 (deleted in 22% of cases and mutated in 3%), a gene with tumor suppressor function in leukemia stem cells of chronic myeloid leukemia." (PMID 23531283, 2013). "Irradiated mice which received transplanted bone marrow from Msr1−/− mice developed chronic myeloid leukaemia (CML) significantly faster than those which received WT cells." (PMID 36325338, 2022).
diabetes (3 papers, 2019 to 2023). "At 30 days, M2 macrophage markers Cd163, Mrc1 and Msr1 (CD204) were decreased in diabetes-prone animals." (PMID 31601915, 2019). "We analyzed the mRNA expression of SRs (LOX-1, MSR1, CXCL16, CD36 and CL-P1) and macrophage markers (CD68, CD11c and CD206) in EAT from 45 patients with IHD (23 with type 2 diabetes mellitus (T2DM) and 22 without T2DM) and 23 controls without IHD or T2DM." (PMID 30894181, 2019).
emphysema (3 papers, 2014 to 2022). "Surprisingly, several studies have suggested MSR1 as a candidate gene for another complex respiratory disease, COPD, and previous research has pointed out that the mechanisms that cause accumulation in the lung of MSR1-expressing macrophages could contribute to severe emphysema and COPD." (PMID 35268530, 2022).
leukemia (3 papers, 2013 to 2024). A malignant (clonal) hematologic disorder, involving hematopoietic stem cells and characterized by the presence of primitive or atypical myeloid or lymphoid cells in the bone marrow and the blood. "In leukemia stem cells, MSR1 has been identified to harbor tumor suppressor gene function." (PMID 38538628, 2024).
tauopathy (3 papers, 2021 to 2025). Neurodegenerative disorders involving deposition of abnormal tau protein isoforms (tau proteins) in neurons and glial cells in the brain. "They proposed that a decline in the severity of tauopathy could be linked to the expression of macrophage scavenger receptor 1 (MSR1) in the invading macrophages." (PMID 39601807, 2025). "Specifically, in the same mouse model of tauopathy that we used here, MSR1 expressed by monocyte-derived macrophages was found to be crucial for the beneficial response to PD-L1 immunotherapy." (PMID 34172073, 2021). "In a tauopathy model strain (VH255) expressing normal human tau in C. elegans muscle, tau aggregation caused paralysis that was alleviated to a similar extent by treatment with 1 μM MSR1 or siRNA against ifp-1, the closest nematode homolog of GFAP." (PMID 35890250, 2022).
Arthritis (2 papers, 2020 to 2022). Inflammation of a joint. "Msr1 knockout mice had elevated viral loads and increased susceptibility to CHIKV arthritis along with a normal type I IFN response." (PMID 33033362, 2020). "Manipulating M2 macrophages through MSR1 may represent a new targeted therapeutic approach for diseases such as cancer, arthritis, and other inflammatory diseases." (PMID 36325338, 2022).
Autoimmunity (2 papers, 2022 to 2024). The occurrence of an immune reaction against the organism's own cells or tissues. "MSR1, a scavenger receptor, is expressed by macrophages and is implicated in immune responses and autoimmunity." (PMID 39224582, 2024). "On the same note, MSR1 has already been associated with autoimmunity and RA development." (PMID 36294757, 2022).
brain infarction (2 papers, 2021 to 2023). Tissue necrosis in any area of the brain, including the cerebral hemispheres, the cerebellum, and the brain stem. "However, clearance of HMGB1 released after cerebral infarction may be partially dependent on the involvement of MSR1 or MARCO, and further studies are warranted to understand the mechanism of removal of HMGB1 released after cerebral infarction." (PMID 37062906, 2023).
breast invasive carcinoma (2 papers, 2019 to 2021). "In breast invasive carcinoma, IRF6 showed the highest rate of alteration (6%) followed by SOX17 and MSR1 (3%)." (PMID 31879572, 2019).
Cognitive impairment (2 papers, 2021 to 2022). Abnormal cognition is characterized by deficits in thinking, reasoning, or remembering. "In a proteomic analysis, NCAN, BCAN, CTSS, MSR1, MDGA1, and CPA2 were reported as upregulated in individuals with PTSD and comorbid mild cognitive impairment." (PMID 35625844, 2022).
colitis (2 papers, 2022 to 2025). Inflammation of the colon. "These EVs are internalized by macrophages via the macrophage scavenger receptor 1 (Msr1), leading to the activation of inflammatory responses and oxidative stress, thereby exacerbating colitis severity." (PMID 40545965, 2025).
colorectal cancer (2 papers, 2022 to 2023). A primary or metastatic malignant neoplasm that affects the colon or rectum. "While in other tumors, such as colorectal cancer, a high expression of MSR1 may be associated with poor prognosis." (PMID 37671167, 2023).
endotoxemia (2 papers, 2020 to 2022). "Macrophage scavenger receptor 1 (MSR1), a member of the scavenger receptor family, participates in many pathophysiological events, such as host defense, endotoxemia, endocytosis, and bone metabolism." (PMID 32066456, 2020). "Further to this, selective and transient depletion of Msr1 in macrophages in vivo resulted in elevated serum concentrations of TNF-α and IL-6 as well as decreased survival rate when mice were challenged with LPS-induced endotoxemia." (PMID 36325338, 2022).
fibrosis (2 papers, 2021). the formation of excess fibrous connective tissue in an organ or tissue in a reparative or reactive process. "Very recently, hepatic macrophage scavenger receptor 1 (MSR1 or CD204) expression was shown to correlate with steatohepatitis, while serum levels of MF activation markers, including sCD163 and sSiglec-7, mostly correlated with NASH-associated fibrosis." (PMID 34831182, 2021).
hemorrhagic stroke (2 papers, 2024 to 2025). A stroke caused by a bleed on the brain. "Immunofluorescence validation confirmed the expression patterns of Lcn2 and Msr1 on MG in the hemorrhagic stroke rat brain 24 h after ICH." (PMID 38988493, 2024).